TNIP1 (TNFAIP3 interacting protein 1)
Diseases named in the same sentence as TNIP1 in open-access papers (continued):
Sharing a sentence is not in itself a finding about the gene and the disease.
systemic lupus erythematosus (38 papers, 2010 to 2025). An autoimmune multi-organ disease typically associated with vasculopathy and autoantibody production. "In a lupus model of ABIN1 (Tnip1)-deficient mice, which have a dysfunction in the regulation of NF-κB, nephritis occurred with the accumulation of Ly6Clo monocytes in the kidneys." (PMID 35371102, 2022). "The TNIP1 gene has been implicated in susceptibility to a number of autoimmune diseases, such as systemic lupus erythematosus (SLE), systemic sclerosis and rheumatoid arthritis (RA)." (PMID 27250029, 2016). "Polymorphisms in the TNIP1 gene encoding A20-binding inhibitor of NF-κB1 (ABIN1) predispose to lupus and other autoimmune diseases in at least eight human populations." (PMID 27807192, 2016). "Consistently, the genes encoding two NF-κB-negative regulators, A20 (also called TNFAIP3) and A20-binding inhibitor of NF-κB1 (ABIN1; also called TNIP1), have been associated with human lupus and lupus nephritis." (PMID 26579219, 2015). "However, present studies mostly focused on the associations between TNIP1 gene polymorphisms and systemic lupus erythematosus." (PMID 29100383, 2017). "TNIP1 has an established role in the immune response, as it encodes a protein that inhibits NFκB and contains polymorphisms that have been associated with risk of systemic lupus erythematosus." (PMID 21750684, 2011). "Experimental overexpression of TNIP1 decreased cells’ responsiveness to irritants and prevented an active state in vitro and a lupus-like autoimmune phenotype was observed in mutant TNIP1 knock-in mice but interestingly not in TNIP1 knock-out ones." (PMID 33581710, 2021). "The single-stranded DNA (ssDNA) sensor, TLR9, also promotes lupus nephritis in lupus-prone Tnip1-/- mice." (PMID 34868046, 2021). "As previously discussed the neighbouring TNIP1 gene (also known as ABIN3) encodes a more obvious regulator of inflammation located in the IRGM genomic region and regulatory variation in this gene has been detected in patients with systemic lupus erythematosus." (PMID 38421405, 2024). "Because polymorphisms in TNIP1 predispose to human lupus and ABIN1[D485N] mice develop spontaneously a disease that closely resembles some types of human SLE, we have continued to investigate the molecular mechanisms driving lupus in this model." (PMID 31694920, 2019). "Indeed, the TNIP1 gene is associated clinically with female-biased autoimmune diseases such as systemic lupus erythematosus and systemic sclerosis, which are diseases characteristic of an over-active immune system and here we also find TNIP1 to be significantly upregulated in female tortoises." (PMID 32846428, 2020). "TNFAIP3 interacting protein 1, TNIP1 (ABIN-1) is involved in inhibition of nuclear factor-κB (NF-κB) activation by interacting with TNF alpha-induced protein 3, A20 (TNFAIP3), an established susceptibility gene to systemic lupus erythematosus (SLE) and rheumatoid arthritis (RA)." (PMID 20849588, 2010). "In lupus models, Ly6Clo monocytes, considered non-classical monocytes, were reported to infiltrate into the kidneys of MRL/lpr mice and ABIN1 (Tnip1)-deficient mice, as well as the central nervous system of NZB/NZW and FcgRIIB-/-Yaa mice." (PMID 40746538, 2025). "Furthermore, the numbers of patrolling monocytes in the kidney are increased in lupus-prone MRL/lpr, B6.Sle yaa, and Tnip1-/- mice." (PMID 34868046, 2021). "Because deleting TLR7 is not sufficient to rescue MRL/lpr or Tnip1-/- mice from nephritis, other TLRs such as TLR9 might also drive the increases in lupus-associated patrolling monocytes in these mice." (PMID 34868046, 2021).
Autoimmunity (21 papers, 2011 to 2025). The occurrence of an immune reaction against the organism's own cells or tissues. "Mice with the orthologous Tnip1 mutation develop spontaneous autoimmunity associated with impaired mitophagy and autophagic silencing of proteins downstream of Toll-like receptor 7 signaling." (PMID 39060650, 2024). "SNP rs960709 regulates the expression of TNFAIP3 Interacting Protein 1 (TNIP1), which plays a crucial role in autoimmunity and tissue homeostasis by encoding an A20-binding protein." (PMID 39314521, 2024). "Another study performed in immune cell line models used H3K27ac HiChIP in order to link SLE risk variants, traditionally associated with the autoimmunity risk gene TNIP1, with enhancer regions, observing that the TNIP1 haplotype extended to neighboring genes." (PMID 33317201, 2020). "These Tnip1 [D485N] mice show age-associated autoimmunity marked by enlarged spleens and circulating levels of antinuclear and anti-DNA antibodies, the latter consistent with the development of severe glomerulonephritis." (PMID 30402506, 2018). "A different group of three SNPs associated with RA mapped to TNIP1, a gene encoding an A20-binding protein that has a role in autoimmunity through the regulation of NFκB activation." (PMID 27508393, 2016). "The genetic signal of association with TNIP1 variants, together with tissular and cellular investigations, suggests that this pathway has a critical role in regulating autoimmunity and SSc pathogenesis." (PMID 21750679, 2011). "Our study established a causative role for TNIP1 variants in human autoimmunity." (PMID 39060650, 2024). "Moreover, single nucleotide polymorphisms (SNPs) in TNIP1 have been associated with several inflammatory diseases and mice deficient for TNIP1 or knock-in for a ubiquitin-binding-defective mutant (TNIP1[D485N]) develop autoimmunity." (PMID 30237509, 2019). "TNF-α-induced protein 3-interacting protein 1 (TNIP1) on chromosome 5q33, also known as VAN, NAF1, ABIN-1, and nip40-1, encodes an A20-binding protein which plays an important role in autoimmunity, chronic inflammation, and cancer through the inhibition of nuclear factor kappa-B (NF-κB) activation." (PMID 27250029, 2016). "TNIP1, a suppressor of the NF-κB pathway, is involved in antiinflammatory response and autoimmunity." (PMID 37781923, 2023). "Because of this, manipulation of TNIP1 expression or function can be a useful tool in modeling autoimmunity in mice for the development of drugs and therapies." (PMID 30402506, 2018). "TNIP1 encodes TNFAIP3 interacting protein 1 and is involved in autoimmunity and tissue homoeostasis." (PMID 28322246, 2017). "Finally, in patients with ambiguous diagnoses of human autoimmunity featuring elevated IgG4 and sicca symptoms, TNIP1-mediated disease may be present and would pave the way for pathway-targeted treatments such as TLR7 and TBK1 inhibitors." (PMID 39060650, 2024).
autoimmune disease (19 papers, 2014 to 2025). A disorder resulting from loss of function or tissue destruction of an organ or multiple organs, arising from humoral or cellular immune responses of the individual to their own tissue constituents. "TNIP1 is a negative regulator of NFκB signaling and polymorphisms in its locus have been associated with a large number of autoimmune diseases." (PMID 31659207, 2019). "Not only does TNIP1 loss or deficiency promotes a hyperinflammatory state, this phenotype closely mimics autoimmune diseases present in human populations." (PMID 30402506, 2018). "In this review, we emphasize receptor signaling complexes and regulation of cytoplasmic signaling steps downstream of TLR given their association with some of the same autoimmune diseases where TNIP1 has been implicated." (PMID 30402506, 2018). "TNIP1 genetic association with certain autoimmune diseases and its negative regulation of inflammatory signaling will be explored in this review." (PMID 30402506, 2018). "Considering the association of TNIP1 with multiple inflammatory and autoimmune diseases as well as the TNIP1-dependent phenotypes observed in animal models, it will be of importance to investigate the relative contribution of TNIP1-dependent necroptosis inhibition we described here." (PMID 30237509, 2019). "With its key regulatory control over multiple signal initiators or pathways, further research on TNIP1 could advance it from association with several autoimmune diseases to a mechanistic contributor to the pathology, and possibly, ultimately, a therapeutic target." (PMID 30402506, 2018). "But, whether TNIP1 gene is also the shared risk gene for GC and autoimmune diseases is unknown." (PMID 27250029, 2016). "By controlling these critical signalling pathways, TNIP1 helps to maintain immune homeostasis and prevent chronic inflammation leading to autoimmune diseases." (PMID 40885730, 2025). "Both TNIP1 and CLTA4 have previously been linked to other autoimmune diseases providing credence to our findings." (PMID 34279044, 2021). "Polymorphisms in four genes encoding proteins that control the MyD88-IRAK4-IRAK1 pathway have been reported to predispose to SLE and other autoimmune diseases in many human populations, namely, TLR7, IRAK1, TNIP1, and TNFAIP3." (PMID 31694920, 2019). "TNIP1 protein is increasingly being recognized as a key repressor of inflammatory signaling and a potential factor in multiple autoimmune diseases." (PMID 30402506, 2018). "GWAS studies predict this predisposition in human populations through multiple recognized SNPs in TNIP1 genes in patients with autoimmune diseases." (PMID 30402506, 2018). "Nevertheless, the predisposition towards hyperinflammatory reactions of multiple cell types with defective TNIP1 function is likely to provide advantageous insights to further study of tissue-specific and whole animal autoimmune disease models as well as testing of new anti-inflammatory therapies." (PMID 30402506, 2018). "As a suppressor of inflammatory signaling downstream of Toll-like receptors (TLRs), TNIP1 could play a pivotal role in specific autoimmune diseases." (PMID 30402506, 2018). "In addition to earlier foundational reports of TNIP1 SNPs in human autoimmune diseases and TNIP1 protein-protein interaction with receptor regulating proteins, more recent studies have identified new potential interaction partners and signaling pathways likely modulated by TNIP1." (PMID 30402506, 2018). "Of 223 hypomethylated regions identified, several were in promoters of autoimmune disease GWAS loci (ARID5B, CD69, HDAC9, IL7R, TNIP1 and TRAF1)." (PMID 32231389, 2020).
systemic sclerosis (12 papers, 2011 to 2023). A chronic disorder, possibly autoimmune, marked by excessive production of collagen which results in hardening and thickening of body tissues. "The TNIP1 rs3792783 SNP, located in an intronic region, has been previously associated with antibody-positive primary Sjögren’s syndrome and systemic sclerosis, and seems to be a risk factor for Vogt–Koyanagi–Harada syndrome." (PMID 30813592, 2019). "Interestingly, CCN2 expression, like S100A9, is increased in the epidermal layers of systemic sclerosis skin, a fibrotic disease state associated with TNIP1 SNPs in patient genomes and TNIP1 protein deficiency in lesional skin." (PMID 32377162, 2020). "In addition, the STR “chr5:151073583” in the intron of TNIP1 was in high LD with the GWAS SNP rs3792783, which is related to systemic scleroderma." (PMID 37045857, 2023). "To investigate the association between TNIP1 and GC risk, we genotyped 4 variants associated with SLE and systemic sclerosis, rs3792792, rs4958881, rs7708392, rs10036748, and analyzed the difference between GC patients and matched controls from the Chinese Han population from Northwest China." (PMID 27250029, 2016). "TNFAIP3 and TNIP1, which are ubiquitin-related genes, have been shown to be correlated with SLE, RA, and systemic sclerosis (SSc)." (PMID 35265070, 2022). "Recently, numerous researches have revealed that TNFAIP3 or TNIP1 gene polymorphisms were associated with susceptibility to some autoimmune inflammatory diseases including systemic lupus erythematous (SLE), systemic sclerosis (SSc), rheumatoid arthritis (RA) and psoriasis." (PMID 31308453, 2019).
rheumatoid arthritis (10 papers, 2010 to 2025). A chronic, systemic autoimmune disorder characterized by inflammation in the synovial membranes and articular surfaces. "Our data also suggest that alterations in mast cell function could contribute to the pathologies linked to genetic polymorphisms in the A20 gene locus or some of its binding partners (for example, TNIP1) that are associated with autoimmune, such as rheumatoid arthritis, or allergic diseases." (PMID 24453940, 2014).
lupus nephritis (9 papers, 2013 to 2021). Glomerulonephritis in the context of systemic lupus erythematosus. "Also, the TNIP1 rs7708392 SNP, also located in an intronic region of TNIP1, has been related to a higher risk of developing lupus nephritis, lupus erythematosus, autoimmune hepatitis, and Sjögren’s syndrome." (PMID 30813592, 2019). "For instance, in Tnip1 [D485N] mice, a lupus nephritis-like presentation is prevented when crossed to backgrounds with catalytically inactive signaling proteins downstream of TLRs such as IRAK-1 or IRAK-4." (PMID 30402506, 2018). "An additional six genes showed an association with lupus nephritis with p <0.001 (PMS2, TNIP1, CARD11, ITGAM, BLK and IRAK1)." (PMID 24386384, 2013).
glomerulonephritis (7 papers, 2016 to 2024). A renal disorder characterized by damage in the glomeruli. "Tnip1–/–Rag1–/– mice, which lack mature T cells and B cells, still developed glomerulonephritis, indicating Ly6Clo monocytes are pathogenic and that adaptive immune system responses were not necessary for kidney pathology." (PMID 35371102, 2022).
amyotrophic lateral sclerosis (5 papers, 2017 to 2025). Amyotrophic lateral sclerosis (ALS) is a neurodegenerative disease characterized by progressive muscular paralysis reflecting degeneration of motor neurons in the primary motor cortex, corticospinal tracts, brainstem and spinal cord. "TNIP1 has been associated with hippocampal sclerosis and amyotrophic lateral sclerosis (ALS)." (PMID 40787599, 2025). "Lastly, we were not able to determine whether the TNIP1 signals colocalized for ADD and amyotrophic lateral sclerosis." (PMID 35379992, 2022).
lymphoma (5 papers, 2016 to 2023). A malignant (clonal) proliferation of B- lymphocytes or T- lymphocytes which involves the lymph nodes, bone marrow and/or extranodal sites. "Somatic mutations in TNIP1 (encoding ABIN-1) have also been found in various human lymphomas, while somatic mutations in NFKBIA (encoding IκBα) have been observed in Hodgkin's disease and in glioblastomas." (PMID 34269817, 2021). "In central nervous system (CNS) lymphoma, the balance between sOPN and iOPN activities has a pro-tumorigenic role, in which iOPN causes transcriptional downregulation of the NF-κB inhibitors, A20/TNFAIP3 and ABIN1/TNIP1, while sOPN promotes receptor-mediated activation of NF-κB." (PMID 36769264, 2023). "On the other hand, sOPN induces NF-κB signaling by acting on cell surface receptors via an autocrine loop without significant change in A20/TNFAIP3 and ABIN1/TNIP1 in lymphoma cells." (PMID 27050077, 2016).
prostate carcinoma (5 papers, 2015 to 2022). A carcinoma that arises from epithelial cells of the prostate gland. "In prostate cancer, miR-210-3p maintains the activation of NF-κB signaling via targeting TNIP1 and SOCS1, resulting in EMT, invasion, migration, and bone metastasis of tumor cells." (PMID 32908121, 2020). "A previous study showed that, miR-210-3p directly binds SOCS1 and TNIP1 through activating NF-κB pathway in prostate cancer cells, resulting in bone metastasis progression of prostate cancer." (PMID 31528235, 2019). "Additionally, miR-210-3p persistently activates the NF-κB pathway by targeting its negative regulator TNIP1 in prostate cancer and therefore promotes EMT, invasion, migration, and bone metastasis." (PMID 35936012, 2022). "Moreover, TNIP1 expression is increased in esophageal cancer and decreased in prostate cancer, suggesting TNIP1 plays different or even opposite roles in different tissue/cell types." (PMID 26046540, 2015). "Studies have shown that miR-210-3p maintains the continuous activation of NF-κB signaling by targeting TNIP1 and SOCS1 and leads to EMT and invasion of prostate cancer cells." (PMID 34853307, 2021).
psoriatic arthritis (5 papers, 2018 to 2024). Joint inflammation associated with psoriasis. "SNPs in TNIP1 (encoding ABIN-1, a component of the A20 ubiquitin-editing complex) are also strongly linked with susceptibility to SLE and psoriatic arthritis." (PMID 34269817, 2021).
viral infection (5 papers, 2013 to 2024). "TNIP1 inhibits interferon-β (IFNβ) promoter activity in response to viral infection or poly(I:C) transfection." (PMID 39060650, 2024).
dermatitis (4 papers, 2015 to 2025). An inflammatory process affecting the skin. "Related to dermatitis, we found an upregulation of CD74, BTLA, TRAF2, TNIP1, and IL19." (PMID 41416938, 2025).
Sepsis (4 papers, 2019 to 2023). Sepsis is defined as life-threatening organ dysfunction caused by a dysregulated host response to infection. "Therefore, it is tempting to speculate that SNPs at the TNFAIP3 and TNIP1 genes leading to low expression or malfunction of the corresponding proteins may be associated with the development and/or the outcome of sepsis." (PMID 30813592, 2019). "Finally, several studies have demonstrated the association of both TNFAIP3 and TNIP1 SNPs with multiple chronic inflammatory diseases, but there has not been any study analyzing their relationship with sepsis." (PMID 30813592, 2019).
anemia (3 papers, 2020 to 2024). A reduction in the number of red blood cells, the amount of hemoglobin, and/or the volume of packed red blood cells. "Notably, Tnip1 sustains cell survival and embryonic development, and Tnip1 deficiency causes embryonic lethality with fetal liver apoptosis, anemia, and hypoplasia." (PMID 37781923, 2023).
coronary heart disease (3 papers, 2015 to 2023). "The TNIP1 (TNFAIP3-interacting protein 1) gene locus that encodes for the protein ABIN1 is associated with the predisposition to SLE is also thought to be significantly associated with other inflammatory-mediated pathologies, including coronary heart disease and myocardial infarction." (PMID 25648164, 2015).
endothelial dysfunction (3 papers, 2015 to 2025). In vascular diseases, endothelial dysfunction is a systemic pathological state of the endothelium (the inner lining of blood vessels) and can be broadly defined as an imbalance between vasodilating and vasoconstricting substances produced by (or acting on) the endothelium. "Endothelial cell-specific FTO knockout mice exhibit protection against DR, and sustained expression of TNIP1 through AAV-mediated gene therapy significantly mitigates diabetes-induced endothelial dysfunction." (PMID 41315216, 2025). "The reduction of TNIP1 relieves the inhibition of the NFκB signaling pathway, resulting in elevated levels of inflammatory factors (e.g., IL-1β and IL-18) and exacerbating retinal vascular inflammation and endothelial dysfunction." (PMID 41315216, 2025).